TPX2 (TPX2 microtubule nucleation factor)
Diseases named in the same sentence as TPX2 in open-access papers (continued):
Sharing a sentence is not in itself a finding about the gene and the disease.
Fanconi anemia (2 papers, 2021 to 2025). Fanconi anemia (FA) is a hereditary DNA repair disorder characterized by progressive pancytopenia with bone marrow failure, variable congenital malformations and predisposition to develop hematological or solid tumors. "Six hub genes (FANCI, KAT2A, TACC3, TPX2, VHL, WSB1) were enriched in Fanconi anemia and HIF-1 pathways, affecting microtubules, spindle formation, and cytoskeleton dynamics during mitosis." (PMID 40832468, 2025).
metastatic disease (2 papers, 2014 to 2016). "Analysis discovered a number of genes previously identified as playing important roles in metastatic disease (e.g., Tpx2, Angptl4, Ezr, Txnip), indicating this strategy is capable of identifying putative metastasis genes on a genome-wide scale." (PMID 27074153, 2016). "Despite this uncertainty, we believe that the results are consistent with TPX2 playing a role in metastatic disease in at least some fraction of human cancers since multiple shRNAs in the 6DT1 cell line result in the same phenotype." (PMID 25368990, 2014).
non-Hodgkin lymphoma (2 papers, 2013 to 2016). Distinct from Hodgkin lymphoma both morphologically and biologically, non-Hodgkin lymphoma (NHL) is characterized by the absence of Reed-Sternberg cells, can occur at any age, and usually presents as a localized or generalized lymphadenopathy associated with fever and weight loss. "It has been shown that the TPX2 gene is amplified in pancreatic tumor tissues and may serve as biomarker for identifying subpopulations of patients sensitive to Aurora-A inhibitor treatment in Non-Hodgkin’s lymphoma." (PMID 24341487, 2013). "Interestingly, TPX2 is also known to interact with the mitotic kinase Aurora A, and the sensitivity of non-Hodgkin lymphoma (NHL) cell lines to the Aurora A inhibitor MK-8745 was increased when TPX2 was depleted with siRNA." (PMID 26976726, 2016).
renal cell carcinoma (2 papers, 2022 to 2025). "TPX2 is also recognized as a potential prognostic and therapeutic marker in the papillary subtype of renal cell carcinoma (PRCC)." (PMID 40362354, 2025).
triple-negative breast carcinoma (2 papers, 2021 to 2023). An invasive breast carcinoma which is negative for expression of estrogen receptor (ER), progesterone receptor (PR), and human epidermal growth factor receptor 2 (HER2). "Our recent data also implicated a role for TPX2 in triple negative breast cancer (TNBC)." (PMID 37770979, 2023). "Moreover, at least some of the relationship between TPX2 and survival is reflected by the enrichment of triple negative breast cancers within the TPX2 high group." (PMID 33622270, 2021).
adrenocortical cancer (1 paper, 2024). "Among these cancer types, high TPX2 expression may be a risk factor for poor prognosis in most cancers, such as adrenocortical cancer (ACC, HR = 2.27, p = 8.6e-7), kidney renal papillary cell carcinoma (HR = 2.08, p = 7.7e-13), and HCC (HR = 1.41, p = 7.4e-8)." (PMID 38833082, 2024).
cervical intraepithelial neoplasia (1 paper, 2015). "Positive surgical margin, HPV persistence, and expression of both TPX2 and PD-L1 are associated with persistence/recurrence of cervical intraepithelial neoplasia after cervical conization." (PMID 26624896, 2015). "CIN, cervical intraepithelial neoplasia; TPX2, xenopus kinesin-like protein 2; IMP3,insulin-like growth factor II messenger RNA (mRNA)-binding protein 3; PD-L1,programmed cell death-1 ligand-1." (PMID 26624896, 2015).
chronic pancreatitis (1 paper, 2023). A chronic inflammatory process causing damage and fibrosis of the pancreatic parenchyma. "In addition, we did not detect significant TPX2 expression levels in non-neoplastic tissue adjacent to invasive PDAC, like exocrine parenchyma, exocrine pancreas with reactive changes and initial chronic pancreatitis, chronic pancreatitis, fat tissue or neural tissue." (PMID 37142730, 2023).
Cirrhosis (1 paper, 2022). A chronic disorder of the liver in which liver tissue becomes scarred and is partially replaced by regenerative nodules and fibrotic tissue resulting in loss of liver function. "We use the bioinformatical analysis to verify that AKR1C3, NQO1, TEK, and TPX2 have good diagnostic performance in patients with cirrhosis." (PMID 36686655, 2022). "The AUCs of expression of AKR1C3, NQO1, TEK, and TPX2 between cirrhosis and HCC were .9.74.77, and .89, proving that the four target genes have predictive value." (PMID 36686655, 2022).
colon adenocarcinoma (1 paper, 2023). "Elevated expression of TPX2 and TTK correlated with an oncogenic state in tumor tissue from patients with colon adenocarcinoma, thus corroborating an oncogenic role for the TPX2/TTK network in the pathogenesis of CRC." (PMID 37770979, 2023).
cutaneous melanoma (1 paper, 2021). A primary melanoma arising from atypical melanocytes in the skin. "Our results revealed several novel biomarkers and biological pathways that participate in the pathogenesis of cutaneous melanoma, and demonstrated the diagnostic and prognostic value of CDC45, CENPF, DTL, FANCI, GINS2, HJURP, TPX2 and TRIP13." (PMID 33531976, 2021).
endometrial endometrioid carcinoma (1 paper, 2025). "Furthermore, patients with endometrial endometrioid carcinoma (EEC) and high expression of TPX2 survived less than 5 years after diagnosis compared to the long‐term survivors." (PMID 40754672, 2025).
endometrial tumor (1 paper, 2022). "CNV mapping onto the entire genome revealed that the TPX2 segment was considerably amplified in the endometrial tumor group when compared with that in the normal endometrial group; these findings were consistent with the TPX2 mRNA expression data." (PMID 35356748, 2022).
fibrosarcoma (1 paper, 2019). A malignant mesenchymal fibroblastic neoplasm affecting the soft tissue and bone. "In parallel with decreased telomerase activities, TPX2 or EXO1 knockdown reduced the viability of fibrosarcoma HTC75 cells and HepG2 cells." (PMID 31179925, 2019).
gallbladder cancer (1 paper, 2024). "Most interestingly three genes TRIP13, NEK2, and TPX2 were identified as key players linked to the development and progression of gallbladder cancer." (PMID 38914609, 2024). "This study, using a network-centric approach, reveals the complex interaction among differentially expressed genes (DEGs) in gallbladder cancer (GBC), highlighting the crucial roles of TRIP13, NEK2, and TPX2 in steering the disease's development and prognosis." (PMID 38914609, 2024).
gastric tumor (1 paper, 2017). "Based on emerging molecular and functional links of FAM83D to mitosis, we hypothesized that FAM83D promotes gastric tumor growth and progression by stimulating cell cycle progression through binding with HMMR, TPX2, and AUKRA." (PMID 29088801, 2017).
invasive breast carcinoma (1 paper, 2021). A carcinoma that infiltrates the breast parenchyma.
ischemic stroke (1 paper, 2021). A stroke disorder caused by obstruction of blood flow to the brain, due to thrombotic (local blood clot formation) or embolic (due to a blood clot or other material traveling from another site) event. "Ultimately, seven downregulated hub genes (including Mki67, Cdk1, Tpx2, Cenpf, Ccnb2, Prc1, and Top2a) were identified as key genes regulated by EA treatment in ischemic stroke by PCR validation." (PMID 34566862, 2021). "A study of Tpx2 also indicated that inhibition of Tpx2 speeded the growth process of axons in cultured neurons, suggesting that the expression of Tpx2 likely regulates neuronal regeneration in ischemic stroke." (PMID 34566862, 2021).
liver fibrosis (1 paper, 2023). "Subsequently, the expression of Anln, Hmmr, Tpx2, Ccnb1, and Ccnb2 was measured in activated hepatic stellate cells (HSCs), which have been shown to become myofibroblast-like cells known to contribute to the progression of liver fibrosis through the deposition of extracellular matrix proteins." (PMID 37566034, 2023).
malaria (1 paper, 2012). Malaria is a serious and sometimes fatal disease caused by a parasite that commonly infects a certain type of mosquito which feeds on humans. "We sought to identify the cellular function of thioredoxin peroxidase-2 (TPx-2), which is expressed in the mitochondria, by disrupting the TPx-2 gene (pbtpx-2) of the rodent malaria parasite Plasmodium berghei." (PMID 23146411, 2012). "The present finding suggests that mitochondrial Prx TPx-2 is not essential for asexual and the insect stage development of the malaria parasite." (PMID 23146411, 2012).
neurofibroma (1 paper, 2013). An intraneural or extraneural neoplasm arising from nerve tissues and neural sheaths. "Genomic changes that accompany the transition of benign neurofibromas to MPNSTs occur at the HMMR/RHAMM locus, the AURKA locus and chromosome 20q (containing AURKA and TPX2)." (PMID 23328114, 2013).
osteoarthritis (1 paper, 2024). A noninflammatory degenerative joint disease occurring chiefly in older persons, characterized by degeneration of the articular cartilage, hypertrophy of bone at the margins and changes in the synovial membrane. "Although many researchers have investigated the function of TPX2 and MMP13 in a variety of cancers and diseases, their specific functions in lipopolysaccharide (LPS)-induced osteoarthritis remain largely unexplored." (PMID 38770093, 2024).
ovarian tumour (1 paper, 2012). "ZNF385B, previously unrecognized as a potential ovarian tumour marker, and VEGFA correlated with overall and progression-free survival, respectively, whereas TPX2 and FOXM1 with optimal CA125 normalization." (PMID 23029477, 2012).
pancreatic adenocarcinoma (1 paper, 2012). "In addition to DPEP1, we also found that higher TPX2 expression is associated with poor outcome in two independent cohorts of resected PDAC patients, supporting the oncogenic role of TPX2 in several solid tumors including pancreatic adenocarcinoma." (PMID 22363658, 2012).
rectal adenocarcinoma (1 paper, 2024). "In contrast, high TPX2 levels may be a protective factor for the prognosis of patients with thymoma (THYM, HR = 0.57, p = 2.3e-3) and rectal adenocarcinoma (READ, HR = 0.45, p = 0.03)." (PMID 38833082, 2024).
retinoblastoma (1 paper, 2023). A malignant tumor that originates in the nuclear layer of the retina. "Particularly, TPX2, KIF20A, CENPA, DLGAP5, and LMNB1 of HHOs were significantly enriched by the retinoblastoma (RB) immunity downregulating PD-L1 expression pathway." (PMID 37240068, 2023).
sarcoma (1 paper, 2021). A usually aggressive malignant neoplasm of the soft tissue or bone. "The weak nature of van der Waals interactions could explain why excess molar amounts of importins were required to inhibit TPX2 condensation, similar to the excess molar of Karyoperhin-2β needed to inhibit fused in sarcoma condensation." (PMID 34302807, 2021).
serous carcinoma (1 paper, 2014). "Interestingly, unlike with all other RAN network proteins investigated, staining for the mitotic RAN partner TPX2 was found exclusively within the nuclei of HG serous carcinomas (p<0.001)." (PMID 24625450, 2014). "Based on Kaplan-Meier analyses, RAN, cytoplasmic XPO7 and TPX2 were significantly associated with poor overall patient survival, and RAN and TPX2 were associated with lower disease free survival in patients with high-grade serous carcinoma." (PMID 24625450, 2014).
thyroid cancer (1 paper, 2018). "Expression levels of TRIP13, TPX2, DLGAP5, KIF2C and TTK were associated with shorter disease free survival (DFS) among differentiated thyroid cancer." (PMID 30386706, 2018).
cancer (163 papers, 2008 to 2026). A tumor composed of atypical neoplastic, often pleomorphic cells that invade other tissues. "BRCA2-deficient cancer exhibits heightened sensitivity to TPX2 and AurkA inactivation through alisertib treatment, which delays mitotic progression." (PMID 40362354, 2025). "Aberrant expression of TPX2 has been reported in various human cancers and is often associated with aggressive tumor behavior." (PMID 40564876, 2025). "Both TPX2 and Aurora A kinase are frequently overexpressed in cancer and are functionally linked to the maintenance of chromosomal instability and aneuploidy." (PMID 40362354, 2025). "Collectively, these studies reinforce TPX2 as a key upregulated factor in ccRCC, strongly linked to poor prognosis and cancer progression." (PMID 40362354, 2025). "Encoding a microtubule-associated protein responsible for spindle assembly, TPX2 was overexpressed in many cancers and significantly correlated with high proliferation and aneuploid tumors." (PMID 40599775, 2025). "TPX2 has already been reported as a key unregulated factor in ccRCC and has been linked to poor patient prognosis and cancer progression." (PMID 40362354, 2025). "The gene TPX2 encodes a microtubule-associated protein and has been established as both a diagnostic and prognostic indicator in various cancers." (PMID 40092988, 2025). "We explored the association of TPX2 expression and cancer-associated fibroblasts (CAF) infiltration using different algorithms." (PMID 38315450, 2024). "In the current study, we observed significantly elevated TPX2 expression in all cancer types and its levels were linked to survival outcomes in at least 20 cancer types." (PMID 38833082, 2024). "As observed for some mitosis‐related proteins, such as Ki‐67 and PCNA, overexpression of TPX2 is associated with poor prognosis in many cancers." (PMID 38466034, 2024). "In summary, our study elucidates the potential of TPX2 as a diagnostic marker for cancer detection and classification, while also underscoring its utility as a prognostic indicator." (PMID 38315450, 2024). "Targeting Protein for Xklp2 (TPX2) is a RanGTP-regulated importin cargo that is overexpressed in many aggressive human cancers and is associated with chromosomal instability." (PMID 38660563, 2024). "Targeting protein for Xenopus kinesin-like protein 2 (TPX2), a well-known mitotic protein, has been linked to carcinogenesis in several cancers." (PMID 38833082, 2024). "The prognostic power of TPX2 in pan-cancers was further revealed, and TPX2 was found to be markedly associated with OS in nearly half of the cancer types." (PMID 38833082, 2024). "TPX2 expression significantly increased in pan-cancers and was associated with survival in nearly half of the cancer types." (PMID 38833082, 2024). "Similar to other proteins that regulate mitosis, TPX2 is overexpressed in a range of different cancers and is generally associated with a poor prognosis." (PMID 35356748, 2022). "The TPX2 expression level was confirmed to correlate with the clinical stage, microsatellite instability, and tumor mutational burden across all cancer types." (PMID 36304254, 2022). "Based on the survival analysis, increased TPX2 expression was associated with a poor prognosis for most cancers." (PMID 36304254, 2022). "We evaluated their respective associations with TPX2 expression in various cancer types to uncover any link between TPX2 activity and mutations in certain cancer types." (PMID 36304254, 2022). "Previously, the interaction between microtubules and TPX2 has been considered as the main mechanism underlying TPX2 in the promotion of cancer cell proliferation and division." (PMID 35444697, 2022). "TPX2 has been strongly implicated in the survival of genomically unstable cancers and targeting of TPX2 in cancer cell lines leads to mitotic arrest and increased genomic instability." (PMID 33622270, 2021).
cancer (continued). "Growing evidence demonstrates that overexpression of CEP55 and TPX2 have been implicated in the development of the ovarian and numerous other carcinomas." (PMID 35540695, 2021). "TPX2 is a risk factor, and co-expression factors were enriched in cell proliferation and cancer-related pathways." (PMID 33154194, 2020). "Our findings show that BRCA2-deficient cancer cells show enhanced sensitivity to inactivation of TPX2 or its partner Aurora-A." (PMID 30177840, 2019). "Depletion of TPX2 or its associated kinase Aurora-A preferentially reduced cell viability in a panel of BRCA2-deficient cancer cells." (PMID 30177840, 2019). "Our results indicate that cancer cells, especially those with defective HR, increasingly depend on the presence of TPX2, or its associated kinase Aurora-A, for their survival." (PMID 30177840, 2019). "Among the top genes found by the PMN, ASXL2, BUB1B, KIF11 and TPX2 have been clinically proven to be associated with multi-cancers, which are a variety of genes commonly identified as mutated in cancers." (PMID 31888692, 2019). "TPX2 expression analyzed by immunohistochemistry was associated with poor patient survival in many types of cancer." (PMID 28069036, 2017). "Aurora A and TPX2 are overexpressed in several types of tumors and have been implicated at different levels in cancer." (PMID 27148480, 2016). "In agreement with our data, other pathway components and Ran-associated genes are also overexpressed in cancer: Aurora kinase A, TPX2, and HSET." (PMID 26683658, 2015). "Our work adds to the multiple indications that Tpx2 is a tumor progression and metastasis-associated gene: TPX2 is overexpressed in a number of cancers." (PMID 25368990, 2014). "Investigation of Aurora kinases and/or TPX2 targeted therapies should be considered in “high risk” early stage cancers." (PMID 23785665, 2013). "For example, the TPX2 gene encodes an Aurora kinase A-stimulated microtubule regulating molecule that when over-expressed in cancer is associated with tumorigenesis." (PMID 23785665, 2013). "The motor-binding targeting protein for Xklp2 (TPX2) is the first cell cycle- associated protein with a restricted pattern of expression and high level of activity found in several malignant tumors." (PMID 24341487, 2013). "Low DPEP1 or high TPX2 expression was associated with poor cancer-specific mortality for all patients in the combined cohort (P<0.01, Kaplan-Meier log rank)." (PMID 22363658, 2012). "This suggests that AURKA and TPX2 are strong candidates for the target of chromosome 20q amplification, and play critical causal roles in cancer development." (PMID 19259408, 2008). "Furthermore, the dysregulation of AurkA and TPX2, adds further diagnostic value, as these proteins are frequently overexpressed in various cancers and are linked to tumor progression and therapeutic resistance." (PMID 39833908, 2025). "TPX2 has also been linked with a variety of cancers, but its relation with hsa-miR-4326 remains unknown." (PMID 41183125, 2025). "TPX2 overexpression has been associated with cancer since its discovery, is reported in several cancer-specific signatures (see, for example,), and almost two decades ago it was found to display the highest correlation score in a gene signature of association with chromosomally unstable tumours." (PMID 39195284, 2024). "MSI had a positive association with TPX2 in 9 cancer types, but negatively associated with COAD." (PMID 38315450, 2024). "Previous studies have shown that elevated phosphorylation level is a pathological hallmark of Lamin degradation in cancer cells; hence, we compared the levels of p‐Lamin A/C (Ser22) in TPX2 KD and control cells, revealing that TPX2 KD decreased the level of p‐Lamin A/C (Ser 22) in OC cells." (PMID 36789877, 2023). "Targeting protein for Xenopus kinesin-like protein 2 (TPX2) is highly expressed in a variety of cancer cells and may be associated with the progression of LUAD." (PMID 37989335, 2023).